XIAP (X-linked inhibitor of apoptosis)
Diseases named in the same sentence as XIAP in open-access papers (continued):
Sharing a sentence is not in itself a finding about the gene and the disease.
prostate carcinoma (continued). "In the current study we wished to determine whether IAP knockdown could sensitise prostate cancer cells to apoptosis, and to investigate the relative contribution of cIAP-1, cIAP-2 and XIAP to this process." (PMID 19549337, 2009). "Furthermore, advanced prostate cancer expressed significant levels of p65 concomitant with XIAP." (PMID 25686839, 2015). "Therefore, our results add support to previous findings that XIAP may be useful as a predictor of prostate cancer progression, which strongly warrants validation in large prospective studies." (PMID 26507126, 2015). "Finally, zinc-chelating agent TPEN degraded XIAP in prostatic carcinoma cells." (PMID 25754465, 2015). "We demonstrated previously that direct small interfering RNA-mediated knockdown of XIAP results in sensitization of PC-3 cells to death ligand-mediated apoptosis, suggesting that depletion of XIAP by itself is sufficient to reverse apoptosis resistance in prostate cancer cells." (PMID 20618956, 2010). "In prostate cancer cells exposed to SFN treatment, a marked decrease in the levels of inhibitor of apoptosis (IAP) family proteins (cIAP-1, cIAP-2 and XIAP) was detected, which was accompanied by inhibition of NF-κB activation." (PMID 41438577, 2026). "The HPA database suggested that C18orf25, DYNC1LI2, SYNJ1, MAPK1, and ARID4B are highly expressed in normal tissues, and CLOCK, SETD2, ZNF654, XIAP, MIS18BP1, and MBTPS2 are highly expressed in prostate cancer tissues." (PMID 36249009, 2022). "XIAP, a downstream factor in the PIM2 pathway in prostate cancer, has been shown to cooperate with PIM2 to inhibit apoptosis in prostate cancer cells." (PMID 33854618, 2021). "In addition, a recent study showed that circ0005276 circular RNA possibly interacted with FUS binding protein (FUS); this RBP-circRNA complex could dysregulate X-linked inhibitor of apoptosis protein (XIAP) transcription, and thereby influence the development of prostate cancer." (PMID 33020462, 2020). "We have recently demonstrated that apigenin suppresses protein expression of XIAP, c-IAP1, c-IAP2 and survivin in human prostate cancer cells." (PMID 26379052, 2015). "As BIRC2 (cIAP1), BIRC4 (XIAP) and BIRC5 (survivin) tended to be co-upregulated in prostate cancer in addition to BIRC6, simultaneous targeting of BIRC6 plus one of these IAP members was more likely to give superior anti-cancer effects." (PMID 25071009, 2014). "Percentages of patients showing positive immunohistochemical reactions to NAIP, Survivin and XIAP in normal prostate (NP), benign prostatic hyperplasia (BPH), prostatic carcinoma (PC) average optical densities of immunostaining in positive patients." (PMID 20078866, 2010). "Furthermore, SH122 suppresses XIAP mRNA expression driven by NF-κB, demonstrating that TRAIL-mediated sensitization by small molecule Smac-mimetic is associated with functional inhibition of both XIAP and NF-κB, especially in androgen-independent prostate cancer." (PMID 19895686, 2009). "In another androgen-independent prostate cancer CL1 cell line, 1 μM of SH122 was sufficient to pull down both XIAP and cIAP-1, and as with DU145, the binding effect was blocked by a 10-fold excess of non-labeled SH122." (PMID 19895686, 2009). "Supporting this idea, a recent report has shown that XIAP, the main Smac/DIABLO target, is a negative regulator of anoikis of circulating prostate cancer cells." (PMID 17067390, 2006). "STAMBPL1 depletion was found to induce apoptosis by promoting the degradation of the protein XIAP, suggesting that targeting STAMBPL1 might offer a promising therapeutic strategy for prostate cancer." (PMID 38419066, 2024). "Similar to our observation, increased XIAP expression was a predictor of a positive outcome in other tumor types, for example, non-small-cell-lung cancer (NSCLS) and lower probability of tumor recurrence in prostate cancer." (PMID 36472768, 2023).
prostate carcinoma (continued). "In prostate cancer, circ0005276 interacts with FUS so as to initiate the transcription of XIAP." (PMID 36747292, 2023). "In prostate cancer cells, Apl-1 treatment increased PARP cleavage and activated caspase-3 expression, and inhibited the expression of anti-apoptotic proteins p-Akt (ser473), p-mTOR (ser2448), XIAP, and Bcl-2." (PMID 35629355, 2022). "In prostate cancer, RNA binding protein FUS, together with a circular RNA (circRNA0005276), can directly bind to the XIAP promoter region, facilitating transcription of XIAP mRNA and thus, increasing the XIAP protein level." (PMID 33138314, 2020). "Embelin treatment of PC3 prostate cancer cells did not decrease XIAP protein levels, and did not increase caspase 9 activation (alone or combined with ionizing radiation) although there was an increase in annexin V and propidium iodide double-positive cells." (PMID 24603802, 2014). "Increased XIAP levels correlate with disease severity in acute myeloid leukaemia and prostate cancer, but not non-small cell lung carcinoma." (PMID 25328816, 2013). "These same XIAP null mice crossed to the TRAMP mouse model of prostate cancer did not result in an alteration in tumor progression, suggesting that XIAP is not a critical regulator of tumor apoptosis in this context." (PMID 20067634, 2010). "In several prostate cancer cell lines (PC3 and LNCaP), the expression of XIAP was perinuclear." (PMID 20078866, 2010). "This discrepancy indicates that XIAP is not the only determinant of TRAIL-resistance in prostate cancer." (PMID 19895686, 2009). "Consequently, circ-XIAP derived from exosomes could enhance the therapeutic effects of DTX, offering predictive chemotherapy sensitizing targets for prostate cancer patients." (PMID 36874026, 2023). "Nevertheless, given that XIAP mRNA levels were not suppressed in cadmium-treated cells, the results of our experiments suggest that NF-κB-controlled pathway is not involved in cadmium-mediated down-regulation of XIAP protein levels in prostate cancer cells." (PMID 20618956, 2010). "Interestingly, in prostate cancer cell lines, no strict correlation has been observed between XIAP expression and TRAIL responsiveness." (PMID 19895686, 2009). "Additionally, CAPE is effective in combating MDR in lung and prostate cancer by downregulating the synthesis of claudin-2, suppressing the NF-κB pathway, diminishing cytoplasmic reserves of GSH (reduced glutathione), and decreasing apoptotic regulators (cIAP1, cIAP-2, and XIAP)." (PMID 39125822, 2024). "In prostate cancer cells, increased expression of PN1 led to substantial reduction of XIAP levels and apoptosis mediated through the uPAR, but not the LRP receptor." (PMID 25686839, 2015). "However, like its effects in prostate cancer or NSCLC cells, YM155 effects on XIAP expression in MKN45 cells were almost not detected." (PMID 22723871, 2012).
pancreatic cancer (71 papers, 2003 to 2025). "In our study shows that NAC can counteract the effects of sulforaphane on the levels of X-linked inhibitor of apoptosis protein and γH2A.X in pancreatic cancer cells." (PMID 39267822, 2024). "While in pancreatic cancer, emodin exerts its antitumor effects by lowering the levels of X-linked inhibitor of apoptosis protein (XIAP) and suppressing NF-kB signaling." (PMID 39272454, 2024). "TRAIL is a therapeutic protein that induces tumor cell death; however, pancreatic cancer cells present intrinsic resistance toward TRAIL by the expression of anti-apoptotic proteins like the X-linked inhibitor of apoptosis protein (XIAP)." (PMID 36834969, 2023). "One study verified that exosomal lncRNA SBF2-AS1, which is derived from M2 macrophages of pancreatic cancer, regulates the level of X-linked inhibitor of apoptosis protein (XIAP) expression by integrating with miR-122-5p." (PMID 34372871, 2021). "Previous studies have shown that XIAP and survivin were overexpressed in pancreatic cancer and were closely associated with cell proliferation and chemoresistance to the standard chemotherapeutic gemcitabine." (PMID 31269745, 2019). "X-linked inhibitor of apoptosis (XIAP), which inhibits caspases, was reported to be suppressed in the lysates of FG-3019-treated murine pancreatic cancers and the effect was most pronounced in the FG-3019 + gemcitabine combination group." (PMID 29719620, 2018). "SiRNAs against KRAS and the apoptosis associated genes BCLXL, FLIP, MCL1L, SURVIVIN and XIAP were transfected into human and murine pancreatic cancer cell lines." (PMID 26716649, 2016). "X-linked inhibitor of apoptosis (XIAP) is a class of anti-apoptotic proteins and is highly expressed in hepatocellular carcinoma, pancreatic cancer and glioma." (PMID 26231038, 2015). "Previous studies attributed the TRAIL resistance of pancreatic cancer cells to the overexpression of X-linked inhibitor of apoptosis (XIAP)." (PMID 22829912, 2012). "GSK-3 inhibition induced anti-survival effects in pancreatic cancer cells, associated with downregulation of NF-κB activity and reduced expression of anti-apoptotic target genes such as XIAP, BcL-XL, and cyclin D1." (PMID 22829912, 2012). "We found that YM155 exerts an anti-proliferative effect in pancreatic cancer cells, inducing cell death through suppression of XIAP (X-linked inhibitor of apoptosis) as well as survivin without affecting the anti-apoptotic proteins Bcl-xL or Mcl-1." (PMID 22723871, 2012). "A high percentage of pancreatic cancer cell lines and tumors express IAPs, including X-linked IAP (XIAP) at elevated levels compared to normal tissue." (PMID 21226944, 2011). "X-linked inhibitor of apoptosis protein (XIAP) is also a critical factor in pancreatic cancer." (PMID 41357196, 2025). "Additionally, XIAP is implicated in resistance to Gemcitabine in pancreatic cancer, and to Carboplatin in ovarian cancer." (PMID 40223934, 2025). "Therefore, our results indicate that NAC counteracted the alterations generated by SFN in X-linked inhibitor of apoptosis protein and γH2A.X levels in pancreatic cancer cells." (PMID 39267822, 2024). "A recent study indicated 6-shogaol sensitized gemcitabine treatment and down-regulate NF-κB activity with its target genes COX-2, cyclinD1, survivin, cellular inhibitor of apoptosis protein-1 (cIAP-1), and X-linked inhibitor of apoptosis protein (XIAP) expression in pancreatic cancer cells." (PMID 30213077, 2018). "Since GSK-3 inhibition efficiently suppresses NF-κB in pancreatic cancer cells, and downregulates NF-κB targets associated with chemotherapy resistance such as XIAP and Bcl-XL, it seemed reasonable to predict that this would also sensitize these cells to gemcitabine." (PMID 19405981, 2009).
pancreatic cancer (continued). "Another research studying the effect of alizarin on pancreatic cancer reported G2/M phase arrest where the proapoptotic protein cleaved caspase 3 was upregulated in contrast to the antiapoptotic-related proteins p-p65, XIAP, Bcl- 2, and c-myc." (PMID 40580306, 2025). "Directly inhibiting XIAP activity shows potential as a therapeutic strategy for pancreatic cancer, namely by targeting the XIAP/caspase axis." (PMID 39267822, 2024). "The overexpression of several IAP family proteins, including cIAP1 and XIAP in pancreatic cancer cells makes them resistant to TRAIL-induced extrinsic apoptosis." (PMID 37503215, 2023). "In 2009, the same group used small molecule XIAP inhibitors in combination with TRAIL to examine the tumor growth of pancreatic cancer cells on the CAM." (PMID 35954398, 2022). "Genetically modified MSCs in combination with XIAP inhibition suppressed metastatic growth of pancreatic carcinoma." (PMID 34249257, 2021). "For instance, loss of lncRNA SBF2-AS1in M2 macrophage-derived exosomes can elevate miR-122-5p to reduce XIAP and repress pancreatic cancer." (PMID 33552977, 2020). "Recent data also demonstrated that a knockdown of survivin or XIAP leads to increased radiosensitivity in various cancer cells, including pancreatic cancer as well as in normal tissue." (PMID 31269745, 2019). "This is highly possible, because survivin, Mcl-1, XIAP, and cIPA2 play critical roles in pancreatic cancer resistance to treatment, and it is also known that survivin, Mcl-1 and XIAP are involved in latent CSC drug resistance and function." (PMID 30285798, 2018). "In order to verify that low XIAP expression increases the sensitivity of pancreatic cancer cells to gemcitabine, we genetically decreased the expression level of XIAP using shRNA." (PMID 28095907, 2017). "High intracellular XIAP levels have been attributed to chemoresistance in many pancreatic cancer cell lines as well as primary tumors." (PMID 28095907, 2017). "In order to exploit XIAP as a putative pancreatic cancer target most efficiently, delivery of its antagonist, the SMAC peptidomimetic, needs to be rendered cancer selective, since a non-selective mimetic would increase the risks for systemic toxicities." (PMID 28095907, 2017). "DIM potentiates chemosensitization and killing of pancreatic cancer cells by downregulation of constitutive as well as drug-induced activation of NF-kappaB and its downstream genes (XIAP, Bcl-xL, survivin, and cIAP)." (PMID 28232946, 2017). "In nude mice model of human pancreatic carcinoma, thymoquinone showed anti-neoplastic and anti-metastatic effects by down-regulating MMP-9 and X-linked inhibitor of apoptosis protein (XIAP)." (PMID 28881699, 2017). "Our laboratory has recently demonstrated that curcumin also induces apoptotic cell death through reduction of the inhibitors of apoptosis (IAP) Survivin, cIAP1, cIAP2 and XIAP at the protein and mRNA levels in pancreatic cancer cells." (PMID 26177391, 2015). "Next, we examined the effects of XIAP silencing via small interfering RNA (siRNA) on two pancreatic cancer cell lines, Capan-2 and AsPC-1, which are resistant to AZD5582." (PMID 26314849, 2015). "Here, we demonstrate that AZD5582, a synthetic small molecule and member of the IAP antagonist family, induces apoptosis in human pancreatic cancer cells by targeting XIAP and cIAP1." (PMID 26314849, 2015). "Here, the XIAP antagonist compounds 1396-11 and 1396-12 were shown to increase radiosensitivity of pancreatic carcinoma in vitro and in a subcutaneous xenograft model in vivo." (PMID 25927408, 2015). "Recent reports have shown that apoptosis is preferentially triggered in pancreatic cancer cells by TRAIL-R1 especially in combination with XIAP inhibitors, whereas stimulation of TRAIL-R2 requires cross-linking for efficient induction of apoptosis." (PMID 23460812, 2013).
pancreatic cancer (continued). "PS treatment for 24 and 48 hours also reduced both XIAP and survivin protein levels in a concentration-dependent manner in pancreatic cancer cells." (PMID 23922886, 2013). "Previous studies also indicated that pancreatic cancer cells suppress the mitochondrial apoptotic pathway by overexpression of Bcl-2, Bcl-xL or XIAP to block the activation of caspases." (PMID 22246103, 2012). "It has been suggested that pancreatic cancer cells have protective mechanisms against the mitochondrial pathway of apoptosis through overexpression of Bcl-family proteins or XIAP to block activation of caspases." (PMID 22246103, 2012). "Taken together, our studies indicate that alpinetin inhibited the proliferation of pancreatic cancer cells possibly through the regulation of the Bcl-2 family and XIAP expression, release of cytochrome c and the activation of caspases." (PMID 22246103, 2012). "We found that alpinetin can induce human pancreatic cancer cells apoptosis, possibly through regulation of the Bcl-2 family and XIAP expression and of the release of cytochrome c." (PMID 22246103, 2012). "In a combined therapy of MSCsTRAIL with XIAP silencing, remission of subcutaneous pancreatic tumors was achieved." (PMID 24212620, 2011). "From literature search we identified the anti-apoptotic genes XIAP, Survivin and Bcl-2 as commonly upregulated in pancreatic cancer." (PMID 20646298, 2010). "For SGS we chose the human pancreatic cancer cell line MiaPaCa-2, which expresses XIAP, Bcl-2 and Survivin and AsPC-1 cells, which express XIAP and Survivin." (PMID 20646298, 2010). "Others have demonstrated that knockdown of XIAP strongly inhibits clonogenicity of pancreatic cancer cells treated with TRAIL indicating that XIAP promotes clonogenic survival of pancreatic carcinoma cells." (PMID 19549337, 2009). "Analysis of the expression of IAPs in pancreatic tumour cells revealed the increased levels of XIAP and Survivin in all three resistant cell lines and, in particular, a very strong overexpression of c-IAP2 in the most resistant PancTuI cells." (PMID 14583775, 2003). "With respect to the relationship of XIAP immunoexpression with patient age and sex in AdCC patients, we detected statistically insignificant differences in XIAP immunoexpression according to patient age and sex, similar to the findings of46 in pancreatic cancer patients." (PMID 41253834, 2025). "XIAP mediates resistance to Docetaxel in prostate, ovarian, and pancreatic cancers." (PMID 40223934, 2025). "Knockdown of lncRNA SBF2-AS1 in exosomes produced by M2 macrophages promotes miR-122-5p expression and decreases XIAP levels, indicating lncRNA SBF2-AS1 could inhibit apoptosis by modulating XIAP via miR-122-5p in pancreatic cancer." (PMID 36338993, 2022). "Eradicated TRAIL-resistant pancreatic carcinoma cells in combination with XIAP inhibitor." (PMID 34249257, 2021). "Additionally, small molecule XIAP inhibitors sensitized pancreatic cancer cells to TRAIL-induced apoptosis via the decrease of XIAP." (PMID 31083595, 2019). "The basis for this potential, and the initiation of this study is that upregulation of antiapoptotic proteins, survivin, Mcl-1, XIAP, and cIPA2 are strongly involved in pancreatic cancer resistance, and that FL118 has been found to inhibit such gene expression in CRC and head-&-neck tumors." (PMID 30285798, 2018). "XIAP has been shown to be involved in resistance of pancreatic cancer to conventional chemotherapy." (PMID 28095907, 2017). "However, we recently performed a similar experiment where we inhibited KRAS and the anti-apoptotic genes BCLXL, FLIP, MCL1L, SURVIVIN and XIAP in a panel of murine and human pancreatic cancer cell lines, including the ones that we employed in the current work." (PMID 28415695, 2017). "To further analyze whether the difference in sensitivity to AZD5582 is dependent on XIAP, we first selected the two pancreatic cancer cells, BxPC-3 and PanC-1, sensitive to AZD5582." (PMID 26314849, 2015).